RAB27A (RAB27A, member RAS oncogene family)
Diseases named in the same sentence as RAB27A in open-access papers (continued):
Sharing a sentence is not in itself a finding about the gene and the disease.
melanoma (continued). "In fact, knockdown of Rab27a suppresses both in vitro cell growth of melanoma cells with Rab27a gene amplification and in vivo tumor growth of melanoma cells where Rab27a-dependent exosome secretion educates bone marrow-derived cells to support tumor growth and metastasis." (PMID 34483204, 2021). "Finally, the participation of Rab27A and Rab27B in management of exosomes has been confirmed in: mouse melanoma, mouse breast cancer, and human squamous cell carcinoma cells for Rab27A and in HeLa cells both for Rab27A and Rab27B." (PMID 34943891, 2021). "Rab27a, a protein known to participate in exosome biogenesis, is overexpressed in melanomas." (PMID 34283059, 2021). "In addition to Rab27a, other Rab proteins such as Rab3a, Rab8, and Rab17 are involved in melanosome transport and distribution, including in melanoma cells, playing an important function in the transfer of melanin from melanocyte dendrites to keratinocytes." (PMID 33072757, 2020). "Rab27a is a regulator of protein trafficking and melanoma proliferation." (PMID 32709086, 2020). "In addition, SFX significantly suppressed the levels of a transcription factor MITF, which can increase the expression of late endosomal proteins, such as RAB7 and CD63, and a main sEV secretion regulator, RAB27a, in melanoma cells." (PMID 30918259, 2019). "Recent studies have revealed that Rab27A and Rab27B control exosome secretion in various cell types, including dendritic cells, cervical cancer cells, breast cancer cells, melanoma cells, bladder cancer cells, and lung cancer cells." (PMID 30081925, 2018). "Rab27A gene amplification was found in 101 melanoma tumor samples, indicating that elevated Rab27A mRNA expression may be due to copy number amplification in melanoma." (PMID 30081925, 2018). "Moreover, Rab27A knockdown reduces lung metastasis of tumors derived from human melanoma cells (SK-Mel-28), murine melanoma cells (B16-F10), and murine 4 T1 mammary carcinoma cells." (PMID 30081925, 2018). "In melanoma, Rab27A regulated vesicular trafficking is reported to drive malignant tumor growth." (PMID 29088864, 2017). "Moreover, RAB27A is upregulated during melanoma progression and it is required for cell division, although by still incompletely defined mechanisms." (PMID 27857118, 2016). "Therefore, the histological and functional results of this study bring physiological relevance to our initial computational data which had revealed a particular enrichment of CPEB4 in melanoma, also characteristic for RAB27A." (PMID 27857118, 2016). "Also, Rab27A inhibition in melanoma cell lines reduced primary tumor growth and development of lung metastasis in xenograft mouse models." (PMID 23665896, 2013). "Rab27A was identified as a driver gene that provides growth advantage during melanoma progression." (PMID 23665896, 2013). "Similarly RAB27a, a gene involved in the regulation of membrane trafficking and exosome formation was highly expressed in a number of melanoma cells." (PMID 22948084, 2012). "Network and/or module based approaches also proved to be powerful in pinpointing disease causing genes, many of which, for example Ppm1l for metabolic syndrome or TBC1D16 and RAB27A for melanoma, have been confirmed experimentally while others are supported by literature evidences." (PMID 23755063, 2012). "First, we tested Rab27a shRNAs in a human melanoma cell line (MeWo) by Western blot." (PMID 21170347, 2010). "In the present study, we focused on B16-F1 melanoma cells and established several KO cells for key factors in melanogenesis, i.e., Tyr, Hps4, Rab27A, and Rab32/38, to determine whether the mechanisms of melanogenesis in melanocytes are retained in B16-F1 cells." (PMID 36430618, 2022). "Upregulated expression of some endosomal–lysosomal-associated genes controlling melanogenesis (e.g., RAB32, RAB38, RAB27A, and RAB33) has been observed in melanoma cells and melanoma patient samples." (PMID 41155412, 2025).
melanoma (continued). "In addition, melanoma cells typically display enhanced secretion activity of extracellular vesicles (EVs) and melanosomes, which may be significantly augmented by the upregulation of RAB27A, RAB32, RAB33A, and RAB38." (PMID 41155412, 2025). "In the current study, melanoma cell treatment increased the expression of MITF and its downstream genes CDK2, c-Met, Bcl2, and RAB27A." (PMID 39684511, 2024). "In summary, we have shown that the Rab27A protein in SkMel28 and DMBC12 melanoma cells controls the migratory and invasion capabilities; however, it does not affect the number and protein concentration of the secreted sEVs." (PMID 39596498, 2024). "MC extract administration induced the amelioration of melanoma by controlling the PAX3/PTEM/PIP3/Akt/mTORC1 and PAX3/MITF/CDK2·c-Met·Bcl2·RAB27A signaling pathways, which are involved in melanoma proliferation and invasion." (PMID 39684511, 2024). "According to previous studies, RAB27A is strongly relevant to the progression of tumors, such as HCC, pancreatic cancer and melanoma." (PMID 30103209, 2018). "Here we showed that this dependency relies in a cluster of genes selectively enriched in melanoma, a feature we functionally demonstrated for MITF and RAB27A." (PMID 27857118, 2016). "They applied the proposed method to a melanoma data set and identified known driver genes in melanoma, along with novel cancer driver genes TBC1D16 and RAB27A." (PMID 23940583, 2013). "The potential engagement of Rab27A and Rab27B in the loading of characteristic protein markers in the sEVs of melanoma cells is not related to their basal expression but is strictly dependent on the particular cell line." (PMID 39596498, 2024). "MITF target genes play important roles in melanoma survival, including inducing an increase in the expression of the antiapoptotic gene Bcl2, cell cycle-related gene CDK2, cell motility-related gene c-Met, and pigment production/secretion-related gene RAB27A." (PMID 39684511, 2024). "In contrast, in extremely aggressive A375 melanoma cells, Rab27A does not participate in either sEV biogenesis, cellular motility, or passage through the ECM." (PMID 39596498, 2024). "Following UVB exposure, there is an upregulation of melanogenesis-related genes—such as microphthalmia-associated transcription factor, tyrosinase, tyrosinase-related proteins 1 and 2, Rab27A and myosin—in both B16F10 mouse melanoma cells and PIG1 human melanocyte cells." (PMID 39203946, 2024). "On the other hand, another study reported that sEV secretion by human metastatic (WM164 and WM983C) and mouse (B16-F10) melanoma cells was independent of Rab27A." (PMID 39596498, 2024). "Moreover, the expressed amounts of RAB5 and RAB27A in breast cancer cells and SK-MEL-28 melanoma cells were significantly reduced after treatment with SFX in a dose-dependent manner." (PMID 30918259, 2019). "Moreover, Rab27A knockdown suppresses exosome secretion in breast cancer cells (MDA-MB-231 and 4 T1), melanoma cells (SK-Mel-28 and B16-F10), and lung adenocarcinoma cells (A529)." (PMID 30081925, 2018). "Transient overexpression of miR-31 in various melanoma cell lines inhibited cell migration and invasion, supporting a role for miR-31 as a tumor-suppressive miR that targets multiple oncogenes such as SRC, MET, NIK and RAB27a." (PMID 22948084, 2012). "Although miR-31 has been shown to act as either an oncomiR or tumor suppressor in various tumor types, in this study we clearly establish miR-31 as a tumor suppressor, demonstrate that it targets multiple oncogenes such as SRC, MET, NIK and RAB27a and regulates the expression of EZH2 in melanoma." (PMID 22948084, 2012). "Our study (based on the NTA and total protein content measurements) demonstrated that CRISPR-mediated knockout of RAB27A in various human melanoma cell lines (A375, DMBC12, and SkMel28) did not decrease the concentration of secreted sEVs or their total protein content." (PMID 39596498, 2024).
melanoma (continued). "Notably, Rab27a is vital for exosomal release of PD-L1 in melanoma, but whether SASP regulates the expression of Rab27a in melanoma is unknown." (PMID 36320056, 2022). "Furthermore, RAB27A-expressing MTEX promoted the invasion phenotype of melanoma cells in contrast to MTEX without RAB27A." (PMID 32709086, 2020). "Furthermore, double RAB27A and RAB27B KO in the A375 cell line did not lead to the inhibition of the number of sEVs released into the culture medium; thus, Rab27B did not compensate for the loss of Rab27A in these melanoma cells, even though Rab27B expression was enhanced significantly in RAB27A KO." (PMID 39596498, 2024).
breast carcinoma (46 papers, 2010 to 2025). "Differential expression of Rab27A was detected in murine xenografts of breast cancer (BC) metastasis and Rab27A was highly associated with the invasive and metastatic potential of human BC cells." (PMID 26070933, 2015). "Overexpression of Rab27a has been associated with the invasive and metastatic potential of human breast cancer cells by promoting the secretion of insulin-like growth factor II (IGF-II), involved in several roles in normal and breast cancer cells such as regulation of VEGF." (PMID 28098821, 2017). "Targeted inhibition of abnormal BC-sEV releasing by Rab27a silence in breast cancer tissue abrogated BCC-induced DOXIC aggravating effects." (PMID 40915108, 2025). "Subsequently, in situ breast cancer mouse models were employed, and a lentivirus expressing an shRNA targeting Rab27a (shRab27a) was intratumorally injected." (PMID 40360476, 2025). "The results showed that Rab27a knockdown significantly reduced the ability of Atg7−/− MEFs to stimulate breast cancer cell malignant progression." (PMID 40707430, 2025). "Roma-Rodrigues and colleagues showed that the number of exosomes released from breast cancer cells decreased significantly by selective silencing Rab27a." (PMID 38495881, 2024). "In mammary carcinoma cells, the decrease of exosome secretion by Rab27a inhibition resulted in a diminution of primary tumor growth and lung metastatic dissemination." (PMID 39008536, 2024). "Rab27a inhibition in mammary carcinoma cells leads to delayed primary tumor growth and lung dissemination by inhibiting EV secretion." (PMID 38495881, 2024). "One example is represented by Rab27a, which showed on one side an exosome-mediated pro-oncogenic role towards a mammary tumor in a mouse model; however, in the second part of the paper, Rab27a silencing resulted in reduced local growth and metastasis." (PMID 38607053, 2024). "In conclusion, our findings demonstrated for the first time that BHMPS regulates the secretory process of intracellular vesicles by disrupting the interaction between Rab27a and Slp4 in breast cancer cells." (PMID 35053535, 2022). "Silencing of Rab27A was found to reduce the secretion of EVs in various tumor cell lines, including melanoma, breast cancer, head and neck cancer, and prostate cancer." (PMID 35565418, 2022). "According to the Human Protein Atlas, high expression of Rab27a decreased the survival rate of renal cancer patients but increased that of breast cancer patients." (PMID 35053535, 2022). "First, the involvement of other Rab27 families in breast cancer invasion and metastasis remains to be elucidated, particularly with regard to how cells select Rab27a among approximately 70 Rab families." (PMID 35053535, 2022). "BHMPS treatment decreased the precipitation of Slp4 compared with that of Rab27a-Myc, indicating that BHMPS inhibited the binding of Rab27a and Slp4 in breast cancer cells." (PMID 35053535, 2022). "Given that Rab27a interacts with Slp4 and Mlph in breast cancer cells, the expression of the two effector molecules was examined." (PMID 35053535, 2022). "Taken together, these results suggest that BHMPS suppressed the migration of breast cancer cells by inhibiting Rab27a expression, which transmitted signals to JNK and FAK activation." (PMID 35053535, 2022). "It has been reported that RAB27A facilitates breast cancer progression by promoting cancer cell invasion and metastasis." (PMID 36371494, 2022). "Here, we demonstrated that BHMPS inhibits migration and invasion of breast cancer cells by blocking the interaction between Rab27a and Slp4." (PMID 35053535, 2022). "Investigating the association between Rab27a expression and patient survival showed that OS in breast cancer patients was longer in the high Rab27a expression group than that in the low Rab27a expression group." (PMID 35053535, 2022).
breast carcinoma (continued). "Rab27a expression was significantly higher in glioblastoma and thyroid carcinoma than in adjacent normal tissues but lower in breast cancer." (PMID 35053535, 2022). "More importantly, blocking either Rab27a or sMSase2 markedly enhances the therapeutic effectiveness of anti-PD-L1 antibody for the inhibition of breast cancer growth." (PMID 33178688, 2020). "A limitation of the present study is that we used a single breast cancer cell line to investigate potential roles of silencing Rab27a and TRAF3IP2 on tumor growth." (PMID 32483202, 2020). "Exosomes derived from Rab27A/B-overexpressing breast cancer cells contain abundant signaling molecules that promote cancer progression." (PMID 30081925, 2018). "Remarkably, downregulating exosome secretion by knocking down the small GTPase Rab27a in tumor cells resulted in decreased primary growth and metastasis in a murine breast cancer model." (PMID 28743887, 2017). "To confirm that the observed effects of DHA on the endothelial cells are dependent on breast cancer exosome secretion and contents, we knocked down the expression of the small Rab GTPase, Rab27A." (PMID 26178901, 2015). "As for Rab27A, high expression of Rab27A promoted invasiveness and metastasis of breast cancer cells by secretion of insulin-like growth factor-II." (PMID 26070933, 2015). "Rab27A has effects on the invasive and metastatic potentials of breast cancer cells by modulating the secretion of IGF-II, which regulates the expression of p16, VEGF, uPA, cathepsin D, cyclin D1, and MMP-9." (PMID 23977139, 2013). "Recently, one report showed that Rab27a affects the invasive and metastatic potential of breast cancer cells by modulating the secretion of IGF-II, which regulates the expression of p16, VEGF, uPA, cathepsin D, cyclin D1, and MMP-9." (PMID 23029308, 2012). "Since estrogen regulates vesicle trafficking gene expression in ER-positive breast cancer cells, it is of interest to determine Rab27A and Rab27B mRNA and protein levels in additional estrogen-dependent carcinomas such as ovarian carcinoma." (PMID 21304180, 2010). "Rab27A mRNA and protein levels increased with the in vitro invasive potential of the breast cancer cells studied." (PMID 21304180, 2010). "To further investigate the role of exosomes in the crosstalk between fibroblasts and breast cancer cells, we generated Atg7−/− MEFs in which Rab27a was constitutively knocked down by short hairpin RNAs (shRNAs), resulting in cells with abnormal exosomal function." (PMID 40707430, 2025). "Consequently, disrupting the RAB27A-mediated EGFR in breast cancer attenuates the metastatic niche, leading to impaired tumor distant metastasis." (PMID 37685910, 2023). "Third, it should be validated whether Rab27a is a critical factor in breast cancer progression and/or metastasis." (PMID 35053535, 2022). "HeLa cells require Rab27a and Rab27b, whereas 4T1 and TS/A breast cancer cells require Rab27a." (PMID 36559315, 2022). "We demonstrated that BHMPS could effectively inhibit the migration potential of breast cancer cells with high expression of Rab27a through down-regulation of FAK and JNK signaling pathways." (PMID 35053535, 2022). "Importantly, Rab27a knockdown and nSMase2 inhibition are more potent suppressors of breast cancer growth compared with anti-PD-L1 antibody treatment." (PMID 33178688, 2020). "Interestingly in the present study, silencing Rab27a or TRAF3IP2 in the breast cancer cell line MDA-MB231 differentially regulated the expression of genes involved in tumor development, growth and metastasis." (PMID 32483202, 2020). "Both Rab27a and TRAF3IP2 play a causal role in breast cancer growth and metastasis." (PMID 32483202, 2020). "It has been observed that in vitro models of breast cancer cells enriched in stemness features and grown as mammosphere showed a high expression of Rab27A (a member of RAS oncogene family), able to increase the exocytosis of EVs, compared to adherent breast cancer cell models." (PMID 30532788, 2018).